GCDH (glutaryl-CoA dehydrogenase)
Diseases named in the same sentence as GCDH in open-access papers (continued):
Sharing a sentence is not in itself a finding about the gene and the disease.
Fever (1 paper, 2020). Body temperature elevated above the normal range. "To investigate how the GCDH-p.Val400Met variant would behave during a fever episode and establish how dietary riboflavin supplementation would influence that behavior, we mimicked fever conditions and evaluated the loss of enzymatic activity and tertiary structure under conditions of thermal stress." (PMID 32992790, 2020).
glioblastoma (1 paper, 2023). The most malignant astrocytic tumor (WHO grade IV). "Gene set enrichment analysis (GSEA) and Gene Ontology analysis revealed that genes linked to IFNα/IFNβ signaling were increased when GCDH was knocked down in glioblastoma stem cells." (PMID 37813874, 2023). "Both, correlative and functional evidence link MYC expression to GCDH expression and histone Kcr protein levels in glioblastoma stem cells." (PMID 37813874, 2023). "Catalytically compromised GCDH in cultured glioblastoma stem cells blocked its function in regulating type I IFN signaling." (PMID 37813874, 2023).
head and neck cancer (1 paper, 2025). A primary or metastatic malignant neoplasm affecting the head and neck. "YEATS2 and glutaryl-CoA dehydrogenase (GCDH) regulate histone crotonylation in head and neck cancer (HNC)." (PMID 40810390, 2025). "Here, we investigated the interplay between a highly expressed epigenetic factor, YEATS2, and a metabolic enzyme, GCDH, in regulating epithelial-to-mesenchymal transition in head and neck cancer." (PMID 40810390, 2025). "Furthermore, we found that the mRNA expression of GCDH was significantly upregulated in head and neck cancer samples relative to their matched normal tissues." (PMID 40810390, 2025). "In conclusion, we have presented a sophisticated interplay between YEATS2 and GCDH, where the upregulation of both factors contributes towards the enhancement of EMT in head and neck cancer by changes in the global EMT-favoring gene expression, mediated through promoter histone crotonylation." (PMID 40810390, 2025).
hepatopathy (1 paper, 2026). "Therefore, this study aimed to define the GCDH variant spectrum in GA1 patients with mild hepatopathy and assess genotype-phenotype correlations." (PMID 42074598, 2026).
Hypoglycemia (1 paper, 2014). A decreased concentration of glucose in the blood. "Interestingly, ammonium accumulation and occasionally hypoglycemia have been reported in a rat 3D brain cell model of GA1 and in GA1 children, respectively, supporting a potential functional interaction between Glud1 and GCDH." (PMID 24498361, 2014).
neuropathy (1 paper, 2024). A disorder affecting the nervous system that manifests with pain, tingling, numbness, and/or muscle weakness. "In the tibial nerve, increased expression of DCXR, GCDH, and TUFM was identified as risk factors for T2DM neuropathy." (PMID 39280009, 2024).
organic acidemias (1 paper, 2021). "With the suspicion of organic acidemias early in her life, the coding regions and splicing sites of GCDH, ETFA, ETFB, ETFDH, IVD were evaluated by PCR and sequencing and no pathogenic variant was identified." (PMID 35083005, 2021).
protein-misfolding disorder (1 paper, 2023). "The broad panel of variant-mediated conformational changes of the GCDH protein supports the classification of GA1 as a protein-misfolding disorder." (PMID 37685964, 2023).
TCA cycle disorders (1 paper, 2014). "Combining lentivirus-shRNA transduction with lysine treatment in the primary neurons further reduced the gene expression of PDC and CS, which demonstrated that GCDH gene silencing can cause TCA cycle disorders." (PMID 25333616, 2014).
type 2 diabetes (1 paper, 2025). "Interventions targeting 2‐AAA/GCDH regulatory loop or CBP/p300‐mediated histone crotonylation represent promising strategies for the treatment of type 2 diabetes." (PMID 40791184, 2025).
metabolic disorder (15 papers, 2013 to 2025). "Glutaric aciduria type 1 (GA-1) is a rare autosomal recessive metabolic disorder caused by the deficient activity of the mitochondrial enzyme glutaryl-CoA dehydrogenase (GCDH)." (PMID 41416259, 2025). "Glutaric aciduria type I (GA-1) is a rare metabolic disorder caused by an autosomal, recessive, inherited deficiency of glutaryl-CoA dehydrogenase." (PMID 39258041, 2024). "Glutaric acidemia type 1 (GA1) is a rare autosomal recessive inherited metabolic disorder caused by variants in the gene encoding the enzyme glutaryl-CoA dehydrogenase (GCDH)." (PMID 37496092, 2023). "Glutaric acidemia type 1 (GA1) is a neurotoxic metabolic disorder due to glutaryl-CoA dehydrogenase (GCDH) deficiency." (PMID 37685964, 2023). "Glutaric acidemia type I (GA-1, OMIM 231,670), an autosomal recessive neurometabolic disorder caused by biallelic pathogenic variants in GCDH resulting in deficiency of glutaryl-CoA dehydrogenase (GCDH), is one of the most common inherited metabolic disorders." (PMID 35897115, 2022).
tumor (7 papers, 2023 to 2025). "Although current studies have highlighted the critical role of histone acetylation in regulating tumorigenesis, tumor progression, and tumor-associated microenvironment, the regulatory mechanisms and functional implications of the GCDH acetylation remain largely unexplored, especially in HCC." (PMID 40896397, 2025). "To assess the in vivo tumor-suppressive effects of GCDH during hepatocarcinogenesis, we utilized a well-characterized Sleeping Beauty (SB) transposon-based hydrodynamic injection model." (PMID 40896397, 2025). "Co-delivery of oncogenic AKT and NRAS with either a control vector or GCDH expression plasmid into the livers of C57BL/6 mice led to full tumor penetrance in both groups." (PMID 40896397, 2025). "Consistent with this, our results showed that GCDH overexpression promotes autophagy and inhibits tumor initiation and development by activating oxidative stress, leading to DNA damage and impaired DNA repair." (PMID 40896397, 2025). "Although the impact of GCDH on lysine metabolism and protein glutarylation has been extensively studied in various tumor types, the regulatory role of GCDH acetylation remains largely unexplored in HCC." (PMID 40896397, 2025). "GCDH overexpression markedly reduced tumor burden and tumor weight and prolonged survival compared to the control group, demonstrating its inhibitory effect on HCC development." (PMID 40896397, 2025). "In vivo models would allow for a more comprehensive understanding of the impact of GCDH on tumor growth, metastasis, and treatment response." (PMID 38745285, 2024). "The expression levels of ACADL, ACADS, ACADSB, ALDH6A1, ETFDH, and GCDH were found to be lower in tumor samples compared to normal samples, whereas the expression levels of CCNB1 and CDK1 were observed to be higher in tumor than in normal samples." (PMID 37994323, 2023). "(C) RT-qPCR result showing enhanced mRNA expression of GCDH in tumor vs. normal samples (n=8)." (PMID 40810390, 2025). "However, our results revealed that GCDH acetylation exerts tumor-suppressive effects on HCC proliferation and metastasis, independently of the regulation of other key enzymes in lysine metabolism." (PMID 40896397, 2025). "GCDH K438 acetylation was critical for its tumor-suppressive function in HCC cells." (PMID 40896397, 2025). "In summary, metformin may suppress tumor growth by inhibiting PLC via GCDH/MRPL45‐mediated fatty acid oxidation and activating the cGMP‐PKG pathway, although this putative mechanism remains to be validated by further studies." (PMID 41189590, 2025). "In addition, analysis of TCGA data revealed down-regulation of GCDH in patients across various tumor types." (PMID 40896397, 2025). "In the in vivo mouse xenograft model, GCDH-K438Q mutant decreased HCC tumor growth, whereas GCDH-K438R mutant increased HCC tumor growth." (PMID 40896397, 2025). "We further investigated the clinical relevance of GCDH in HCC patients and found that its expression was inversely correlated with tumor grade in both the TCGA and ICGC-LIRI-JP cohorts." (PMID 40896397, 2025). "(E) Representative IHC images showing the levels of ECHS1, GCDH, YEATS2, H3K27cr, and Twist1 in HNC normal vs. tumor tissue samples (n=8) (Scale bar, 100 μm)." (PMID 40810390, 2025). "Collectively, our findings demonstrate that the acetylation of GCDH at lysine 438 (K438), mediated by P300 and HDAC1, plays a vital role in the tumor-suppressive activities of HCC cells." (PMID 40896397, 2025). "ECHS1 expression was notably reduced in tumor tissues, whereas GCDH, YEATS2, H3K27cr, and Twist1 exhibited increased staining intensity in tumor sections compared to the adjacent normal tissues." (PMID 40810390, 2025). "In vivo tumor xenograft assays showed that GCDH overexpression markedly inhibited HCC tumor growth, whereas GCDH knockdown markedly enhanced tumor development." (PMID 40896397, 2025).
tumor (continued). "Statistical analysis revealed a marked negative correlation between GCDH expression and serum α-fetoprotein (AFP) levels, as well as an association with the absence of tumor capsule formation." (PMID 40896397, 2025). "Additionally, we performed IHC to evaluate the levels of ECHS1, GCDH, YEATS2, H3K27cr, and Twist1 in HNC tumor and their matched normal tissue sections." (PMID 40810390, 2025).
cancer (6 papers, 2021 to 2025). A tumor composed of atypical neoplastic, often pleomorphic cells that invade other tissues. "By modulating this posttranslational modification (PTM), GCDH exerts significant control over metabolic pathways that are essential for the initiation and progression of malignant tumors." (PMID 40896397, 2025). "As per the evidence provided by us, it could be proposed that the surge in GCDH in YEATS2-high cancer cells affects the chromatin by increasing the pool of crotonyl-CoA inside nucleus, which acts as a substrate for histone-modifying enzymes." (PMID 40810390, 2025). "Given that ROS might have a marked impact on suppressing cancer cell metastasis through GCDH-mediated autophagy and DNA damage, we investigated whether the ROS inhibitor N-acetyl-l-cysteine (NAC) could modulate these downstream effects." (PMID 40896397, 2025). "We found that GCDH was upregulated and had an inverse pattern of expression with the downstream enzyme ECHS1 (Enoyl Coenzyme A hydratase, short chain 1) in TCGA cancer vs. normal tissue dataset." (PMID 40810390, 2025). "The study of SCP2, ABCD3, MICOS10, GCDH, and MTRF1L genes' immune infiltration and cancer correlation in CRC offers a fresh perspective." (PMID 40620061, 2025). "While exploring the relationship of YEATS2 with cancer cell metabolism, we found that YEATS2 is co-expressed with crotonyl-CoA producing GCDH (glutaryl-CoA dehydrogenase) in HNC, and the downregulation of either of these two genes led to a decrease in H3K27cr levels in HNC cells." (PMID 40810390, 2025).
infection (2 papers, 2013 to 2020). The state of being infected such as from the introduction of a foreign agent such as serum, vaccine, antigenic substance or organism. "Our constructed lentiviral vector displayed high infection efficiency in primary striatal neurons and remarkably suppressed the expression of GCDH gene." (PMID 23658800, 2013).
GCDH also shares sentences with these, for which no sentence is quoted: nephrotic syndrome (2 papers); bacterial infections (1); chalazion (1); Charcot-Marie-Tooth disease (1); cognitive decline (1); cystic fibrosis (1); developmental delay (1); Diarrhea (1); diarrheal disease (1); Fundus dystrophy (1); gastroenteritis (1); glioma (1); glutaric acidemia (1); glutaric acidemia type II (1); Immunodeficiency (1); insulin-dependent diabetes mellitus (1); Intellectual disability (1); Lesch Nyhan disease (1); nemaline myopathy (1); nephronophthisis (1); nephropathies (1); neurodegenerative disease (1); non-syndromic intellectual disability (1); Organic aciduria (1); pneumonia (1); rheumatoid arthritis (1); Uterine leiomyoma (1).